MARCKS (myristoylated alanine rich protein kinase C substrate)
Diseases named in the same sentence as MARCKS in open-access papers (continued):
Sharing a sentence is not in itself a finding about the gene and the disease.
psychiatric diseases (2 papers, 2010 to 2015). "Additionally, altered MARCKS levels have been implicated in a number of mental disorders, and have been observed in schizophrenia and depression patients, as well as violent suicide completers." (PMID 26528135, 2015). "Surprisingly, it is possible that MARCKS has unknowingly been targeted for decades in the treatment of psychiatric disorders." (PMID 26528135, 2015). "In addition, we considered the involvement of the genes in psychiatric diseases and we narrow down to MARCKS and SYT1." (PMID 20098743, 2010).
bacterial infection (1 paper, 2017). "Although MARCKS phosphorylation by the conventional PKC-α has been previously found to facilitate zymosan adherence to macrophage cells and promote phagocytosis, the role of novel PKC isoforms on MARCKS function in response to bacterial infection has not yet been investigated." (PMID 28638804, 2017).
blood cancers (1 paper, 2021). "MARCKS has also been observed to possibly contribute to some risk factors that predispose the development of several blood cancers." (PMID 33958003, 2021). "In addition to its role in the development and progression of hematological malignancies, MARCKS has been implicated in defining the overall outcome in several blood cancers." (PMID 33958003, 2021). "Hence, patients with “MARCKS-driven blood cancers” have a higher risk of disease progression or recurrence and an overall worse prognosis." (PMID 33958003, 2021). "Recently our lab made use of these peptidomimetics for the very first time to target MARCKS in blood cancer." (PMID 33958003, 2021). "Such conflicting reports regarding the behavior of MARCKS have been reported in other blood cancers as well." (PMID 33958003, 2021). "Although we are at a very early stage to draw a conclusion, the body of knowledge that we have until now demonstrates that MARCKS is strongly involved in the development and progression of several blood cancers." (PMID 33958003, 2021). "Additionally, we will highlight the importance of MARCKS as a valuable therapeutic target in blood cancers and will discuss the potential of existing strategies available to tackle MARCKS-driven blood cancers." (PMID 33958003, 2021). "By disposing of the abundant ubiquitinated proteins MARCKS was observed to prolong therapeutic resistance by possibly circumventing unfolded protein response which is also a common occurrence in other bortezomib-resistant blood cancers." (PMID 33958003, 2021). "Such a dual role of MARCKS has been observed in blood cancers as well." (PMID 33958003, 2021). "Within blood cancers, although there are several studies that have identified a potent role of deregulated MARCKS with the overall process of carcinogenesis, yet our overall understanding of the regulatory roles of the gene and the associated protein remains at a nascent stage." (PMID 33958003, 2021). "Although, a probable therapeutic constraint may be observed in blood cancers which are driven by the unphosphorylated form of MARCKS." (PMID 33958003, 2021). "Consequently, targeting MARCKS, whether directly or indirectly, is a viable therapeutic alternative with landmark clinical repercussions for the treatment of several solid and blood cancers." (PMID 33958003, 2021). "Interestingly, the role of MARCKS as a prognostic biomarker in blood cancers has not been explored significantly, despite its strong involvement in therapeutic resistance." (PMID 33958003, 2021).
cardiovascular disease (1 paper, 2020). "Whatever the outcome of these future experiments, the present study provides the first evidence that MARCKS has a critical role in regulating vascular contractility and offers a potential new target for modulating contractility in treating cardiovascular disease." (PMID 32707323, 2020).
hematological malignancies (1 paper, 2021). "In this review, we will investigate the current body of knowledge and evolving concepts of the physical properties, molecular network, functional attributes, and the likely pathogenic roles of MARCKS in hematological malignancies." (PMID 33958003, 2021). "Compelling preclinical in vitro and in vivo evidence suggests that MARCKS plays a critical role in the development and progression of several hematological malignancies." (PMID 33958003, 2021). "Several reports have identified MARCKS as a positive regulator of the carcinogenesis process in multiple hematological malignancies." (PMID 33958003, 2021). "Indeed, with an improved structural and functional understanding of MARCKS, there exists a strong potential to develop novel therapies to better tackle MARCKS-driven pathophysiology in hematological malignancies." (PMID 33958003, 2021). "Similarly, aberrant MARCKS has been observed to contribute to increased cell proliferation, reduced cell death, higher rates of cell migration, invasion, and motility, and malignant transformation in several hematological malignancies." (PMID 33958003, 2021).
MARCKS also shares sentences with these, for which no sentence is quoted: hepatocellular carcinoma (5 papers); bipolar disorder (2); COVID-19 (2); Parkinson disease (2); renal carcinoma (2); acute leukemia (1); adenocarcinoma (1); anorexia nervosa (1); Anxiety (1); arteriolosclerosis (1); Astrocytoma (1); atherosclerosis (1); bronchitis (1); chronic lymphocytic leukemia (1); chronic myelogenous leukemia (1); cognitive disorder (1); communicable diseases (1); cystic fibrosis (1); endometrial cancer (1); frontotemporal lobar degeneration (1); glioma (1); liver cancer (1); liver tumor (1); lymph node metastatic tumors (1); metastatic melanoma (1); Obesity (1); omphalocele (1); pulmonary hypertension (1); respiratory diseases (1); sarcopenia (1).
A further 3 diseases each share a sentence with MARCKS in 1 paper.